IFNA17 (interferon alpha 17)
Description:
Produced by macrophages, IFN-alpha have antiviral activities. Interferon stimulates the production of two enzymes: a protein kinase and an oligoadenylate synthetase.
Synonyms: LEIF2C1; IFN-alphaI; IFNA; INFA
Tractability: Antibody: a drug acting on it is in phase 2 or 3 trials; its Gene Ontology location is reachable by antibodies, with high confidence; UniProt places it where antibodies can reach, with medium confidence; UniProt predicts a signal peptide or a membrane-spanning region.
Gene: Protein-coding gene on chromosome 9 (21,227,243 to 21,228,222, reverse strand). Ensembl gene ENSG00000234829.
Subcellular location: Secreted
Pathways (Reactome):
Immune System: Interferon alpha/beta signaling; Regulation of IFNA/IFNB signaling; TRAF6 mediated IRF7 activation
Disease: Evasion by RSV of host interferon responses; SARS-CoV-2 activates/modulates innate and adaptive immune responses
Hemostasis: Factors involved in megakaryocyte development and platelet production
Gene Ontology:
Molecular function: cytokine activity; type I interferon receptor binding; cytokine receptor binding
Biological process: adaptive immune response; B cell activation involved in immune response; cellular response to virus; humoral immune response; natural killer cell activation involved in immune response; response to exogenous dsRNA; response to virus; T cell activation involved in immune response; type I interferon-mediated signaling pathway; defense response
Cellular component: extracellular region
Genetic constraint (gnomAD): Loss-of-function variants: 0 observed, 0.29 expected, observed/expected ratio (o/e) 0, 90% interval 0 to 1.87. That is too few expected variants to judge how well the gene tolerates losing a copy. Missense variants: 285 observed, 212.45 expected, observed/expected ratio (o/e) 1.34, 90% interval 1.22 to 1.48. Synonymous variants: 107 observed, 78.54 expected, observed/expected ratio (o/e) 1.36, 90% interval 1.16 to 1.6.
Homologues: Orthologues: chimpanzee IFNA17 (97% identical), macaque IFNA21 (92% identical), macaque IFNA10 (92% identical), pig IFN-ALPHA-9 (69% identical), pig IFN-ALPHA-13 (68% identical), pig IFN-ALPHA-15 (68% identical), pig IFN-ALPHA-8 (68% identical), pig IFNA1 (67% identical), pig IFN-ALPHA-4 (66% identical), pig IFN-ALPHA-17 (65% identical), pig IFN-ALPHA-1 (64% identical), pig IFN-ALPHA-10 (64% identical), and 33 more. Paralogues in human: IFNA4 (96% identical), IFNA10 (95% identical), IFNA7 (92% identical), IFNA21 (91% identical), IFNA16 (87% identical), IFNA14 (83% identical), IFNA5 (83% identical), IFNA2 (80% identical), IFNA6 (80% identical), IFNA8 (80% identical), IFNA13 (79% identical), IFNA1 (79% identical), and 4 more.
Diseases named in the same sentence as IFNA17 in open-access papers:
IFNA17 is named in the same sentence as 30 diseases in open-access papers, as found by Europe PMC text mining. Sharing a sentence is not in itself a finding about the gene and the disease. The quoted sentences say what the papers report.
COVID-19 (5 papers, 2020 to 2025). A disease caused by infection with severe acute respiratory syndrome coronavirus 2. "In support of this data, IFNA17 was discovered to be differentially expressed in a study evaluating interferon-stimulated gene profiles of post-mortem lung tissues from severe cases of COVID-19." (PMID 40429886, 2025).
influenza (5 papers, 2010 to 2024). An acute viral infection of the respiratory tract, occurring in isolated cases, in epidemics, or in pandemics; it is caused by serologically different strains of viruses (influenzaviruses) designated A, B, and C, has a 3-day incubation period, and usually lasts for 3 to 10 days. "Similar to influenza stimulation, vaccinia-stimulated PBMCs and monocytes shared multiple interferon-encoding genes, such as IFNA7, IFNA17, among their top DEGs." (PMID 37600811, 2023).
viral infection (4 papers, 2017 to 2025). "IFNA17 is an interferon that is a critical part of the innate immune response in viral infection." (PMID 40429886, 2025).
AIDS (1 paper, 2024). A syndrome resulting from the acquired deficiency of cellular immunity caused by the human immunodeficiency virus (HIV). "Additionally, patients with Acquired Immunodeficiency Syndrome (AIDS; stage C) showed significantly higher expression of IFNA1/13, IFNA8, IFNA14, IFNA16, IFNA17, and IFNA21 mRNA." (PMID 38543729, 2024).
Alzheimer disease (1 paper, 2022). A progressive, neurodegenerative disease characterized by loss of function and death of nerve cells in several areas of the brain leading to loss of cognitive function such as memory and language. "It is important to note that CDKN2A and IFNA17 were enriched in Alzheimer’s disease." (PMID 36506471, 2022).
benign prostatic hyperplasia (1 paper, 2023). A non-cancerous nodular enlargement of the prostate gland. "Results showed that the IFNA17 cytokine was upregulated in primary prostate cancer samples compared to the benign prostatic hyperplasia (BPH) group, and higher levels of IFNA17 were found in CRPC patients than in the BPH or primary prostate cancer groups." (PMID 37142586, 2023).
cervical cancer (1 paper, 2023). A primary or metastatic malignant neoplasm involving the cervix. "The IFNA17 184Ile allele is associated with an increased risk of cervical cancer, suggesting that IFNA17 polymorphisms may be key biomarkers of cervical cancer susceptibility." (PMID 37142586, 2023).
dementia (1 paper, 2021). Loss of intellectual abilities interfering with an individual's social and occupational functions. "Next, we verified selected genes in the type I IFN signature in our patient cohort by RT-qPCR, which confirmed their differential regulation in sPD patients and those with dementia, including IFNA17, IFNB, and IFNAR1." (PMID 34234281, 2021).
Haemorrhagic Fever (1 paper, 2020). "Moreover, polymorphisms in IFNA17 have been associated with a 3.6-fold increased risk for Crimean-Congo Haemorrhagic Fever development." (PMID 33092534, 2020).
Hepatitis C (1 paper, 2020). "It has been shown in vitro that IFNA17 is three times more efficient against Hepatitis C than IFNA2A, which is the most effective current treatment." (PMID 33092534, 2020).
melanoma (1 paper, 2020). A malignant, usually aggressive tumor composed of atypical, neoplastic melanocytes. "The IFNA17 transcript showed no expression in the primary melanoma group, and little expression in the metastatic samples when compared to absolute expression values from the other transcripts." (PMID 32431053, 2020).
metastatic prostate carcinoma (1 paper, 2023). A carcinoma that arises from the prostate gland and has spread to other anatomic sites. "We validated the association between IFNA17 levels and tumor grade and confirmed that IFNA17 was enhanced in primary and metastatic prostate cancer samples compared to those in normal prostate and in prostate cancer samples with high Gleason scores." (PMID 37142586, 2023). "We demonstrated the abundance of the IFNA17 protein in CHRM4-overexpressing cells and the serum of patients with metastatic prostate cancer, suggesting that IFNA17 is a potential prognostic marker for advanced prostate cancer." (PMID 37142586, 2023).
prostate carcinoma (1 paper, 2023). A carcinoma that arises from epithelial cells of the prostate gland. "To determine the clinical relevance, we examined IFNA17 cytokine concentration released by prostate cancer patients using sera collected from the Taipei Medical University-Wan Fang Hospital (Taipei, Taiwan)." (PMID 37142586, 2023). "Mechanistically, CHRM4-driven AKT/MYCN signaling upregulated the interferon alpha 17 (IFNA17) cytokine in the prostate cancer TME after ADT." (PMID 37142586, 2023). "We found a correlation between CHRM4 and IFNA17 cytokine response signaling in the TME of prostate cancer, in which abundant IFNA17 was found in prostate cancer cells cocultured with CM collected from M2-type TAMs." (PMID 37142586, 2023). "We found that increased IFNA17 protein expression was associated with induction of CHRM4, phosphorylated (p)-AKT, and MYCN proteins in prostate cancer cells, but decreased expression of these proteins was observed after DHT treatment." (PMID 37142586, 2023). "MYCN-driven PDL1 was significantly elevated when prostate cancer cells were cultured under ADT conditions or with IFNA17 treatment, and its expression decreased after CHRM4-KD." (PMID 37142586, 2023). "In our study, the advanced CRPC group had significantly higher IFNA17 levels than did the primary prostate cancer group, and both cancer groups had higher IFNA17 levels than the BPH group." (PMID 37142586, 2023). "Abundant CHRM4-driven AKT/MYCN signaling upregulates interferon alpha 17 (IFNA17) cytokine activity in prostate cancer after ADT." (PMID 37142586, 2023). "We hypothesized that ADT-induced abundance of the MYCN transcription factor in prostate cancer cells might allow it to bind to the E-box on the IFNA17 regulatory sequence." (PMID 37142586, 2023). "We demonstrated that CHRM4/IFNA17-activated prostate cancer cells might interact with M2-type TAMs to promote NED and immune checkpoint pathways in prostate cancer cells, contributing to the development of an immunosuppressive TME and NEPC." (PMID 37142586, 2023). "Analysis of CHRM4-driven IFNA17 cytokine release in the prostate cancer TME following ADT resistance may provide a clear understanding of the feedback loop consisting of CHRM4/AKT/MYCN in the context of AR inhibition." (PMID 37142586, 2023). "In addition, tissues expressing high IFNA17 levels were negatively correlated with AR-responsive gene signatures, as revealed by GSEAs in TCGA prostate cancer datasets (GO, Nelson, Wang, PID)." (PMID 37142586, 2023). "Next, we determined IFNA17 protein levels in various prostate cancer cell lines." (PMID 37142586, 2023). "Our study evaluated serum IFNA17 levels in patients with prostate cancer." (PMID 37142586, 2023). "We demonstrated that IFNA17 overexpression might enhance functional characteristics, such as migration, proliferation, and association with elevated levels of CHRM4, NE markers, and immune checkpoints in prostate cancer cells." (PMID 37142586, 2023). "In summary, we found that ADT-induced IFNA17 expression positively affected the elevation of NED and immune checkpoint abundances in prostate cancer cells, which was dependent on CHRM4." (PMID 37142586, 2023). "Positive correlations between CHRM4 and IFNA17 at the messenger (m)RNA and protein levels, functional characteristics, and clinical datasets were found in advanced and NEPC-like prostate cancers." (PMID 37142586, 2023). "In summary, IFNA17 cytokine secretion may be positively correlated with CHRM4 abundance, and may be involved in NED progression in advanced prostate cancer." (PMID 37142586, 2023). "IFNA17 mediates a feedback mechanism in the TME by activating the CHRM4/AKT/MYCN signaling-driven immune checkpoint pathway and neuroendocrine differentiation of prostate cancer cells." (PMID 37142586, 2023).
prostate carcinoma (continued). "Our findings suggest that ADT-induced CHRM4 may activate AKT/MYCN signaling to induce IFNA17 secretion and upregulate immune checkpoints in the TME to drive potential immunosuppressive responses, leading to NED and metastasis in prostate cancer." (PMID 37142586, 2023).
bacterial infections (1 paper, 2020). "Data showed that females exhibit higher levels of anti-viral type 1 interferons IFNA17, IFNA2, IFIT1, IFIT3 and IFNE in the immune tissues/cells, which serve as the first line of defense against viral and bacterial infections." (PMID 33271804, 2020).
IFNA17 also shares sentences with these, for which no sentence is quoted: infection (9 papers); cancer (3); pneumonia (2); tumor (2); anaemia (1); co-infection (1); connective tissue disease (1); dengue (1); Insulin resistance (1); lupus nephritis (1); melanocytic neoplasm (1); multiple sclerosis (1); primary Sjögren’s Syndrome (1); systemic lupus erythematosus (1); viral central nervous system infection (1); viral diseases (1).